CD47 (CD47 molecule)
Diseases named in the same sentence as CD47 in open-access papers (continued):
Sharing a sentence is not in itself a finding about the gene and the disease.
tumor (continued). "The data suggest an important role for CD47 in TIICs found in the periphery of the tumor." (PMID 36171566, 2022). "Besides, our results shed light on the significant role of CD47 in tumor immunity and metabolic activity." (PMID 35697717, 2022). "Lastly, chemotherapy may pre-condition tumors by recruiting more inflammatory cells to infiltrate the tumor, allowing anti-CD47 blockade to work on more cells." (PMID 36429020, 2022). "Antibodies against LAG-3, TIM-3, TIGIT, CD47, and B7-H3 are the most advanced IC blockade drugs and may be approved for the treatment of specific tumor types in the near future, depending on the results of the trials." (PMID 35164813, 2022). "Because myeloid cells are recruited, combining CD47-SIRPα checkpoint inhibition with IgA antibodies might be a good method for targeting resistant tumor cells." (PMID 35865547, 2022). "In a similar mouse model, but a different approach to interrupting the CD47-SIRPα signaling, QPCTL deficient Ba/F3-HER2 cells that lack pyroglutamate on CD47, were effectively killed by neutrophils directed to the tumor by IgA-HER2, in a similar fashion to CD47KO Ba/F3-HER2 cells." (PMID 35865547, 2022). "Expression of CD47 in cancer cells contributes to immune evasion and subsequent tumor progression." (PMID 35229723, 2022). "This neoplasm is characterized by overexpression of CD47, and it has been found that the use of B6H12.2, or other monoclonal antibodies, either promotes CD47 decrease or the stimulation of phagocytosis by macrophages, highlighting the importance of this receptor in the maintenance of this neoplasm." (PMID 36293358, 2022). "CD47 inhibits phagocytosis of macrophages through high expression on tumour cells." (PMID 36310169, 2022). "CD47-SIRPα signaling is an important component of the tumor immune microenvironment." (PMID 36454036, 2022). "In addition, tumor cells can express the “don’t eat me” signal protein such as CD47 and CD24 on the cell membrane to avoid the phagocytosis of macrophages and achieve immune escape." (PMID 36558902, 2022). "Since direct tumor cell killing activity has been reported for several anti-CD47 antibodies." (PMID 35664753, 2022). "For tumor cells such as A549, the ability of CD47-specific ADCs to stimulate phagocytosis may overcome the limitation of insufficient cytotoxicity." (PMID 35646646, 2022). "The researchers used transmembrane region structure of platelet-derived growth factor receptors and SIRPα avariant co-modified exosomes (SIRPα-exosomes), which can destroy the interaction of CD47-SIRPαleads to increase the number of cells phagocytized by macrophages, thereby inhibiting tumor growth." (PMID 34973131, 2022). "In addition, KA, which is characterized by rapid tumor growth till 1–2 cm, showed higher CD47 expression compared to NS and AK." (PMID 36010209, 2022). "Firstly, CD47 ligation induce apoptosis of tumor cell through a caspase-independent mechanism." (PMID 36081498, 2022). "CD47 is a transmembrane protein which is highly expressed in some tumour cells, including PDAC." (PMID 35626020, 2022). "CD47–SIRPα blockade can enhance the phagocytic activity of phagocytes to eliminate tumor cells." (PMID 35464451, 2022). "The recombinant anti-CD47 tumor vaccine has an effectual antitumor activity and may be a promising antitumor agent." (PMID 35837100, 2022). "In preclinical studies, NI-1701 triggered potent antibody-dependent cellular phagocytosis (ADCP) and cytotoxicity (ADCC) of tumor B cells in vitro, through co-engagement of CD47 and CD19, and controlled tumor progression of B-cell lymphoma and leukemia xenograft models." (PMID 35538512, 2022). "Also, low-dose cyclophosphamide is used to improve Daratumumab-mediated ADCP against tumor cells, probably mediated by increased expression of FcγR on macrophages and reduced CD47 levels on tumor cells." (PMID 35342342, 2022).
tumor (continued). "Treatment with anti-CD47 antibodies could represent a potent therapy for SGCs by promoting the phagocytic clearance of tumor cells through various mechanisms." (PMID 36171566, 2022). "Using CD47 signaling for tumor therapies is feasible and attractive." (PMID 35978433, 2022). "These antagonists include 1) monoclonal antibodies targeting CD47 or SIRPα, 2) SIRPα-Fc fusion proteins, 3) bispecific antibodies (BsAb), 4) small molecules to down-regulate CD47 on tumor cells, 5) RNAi and, 6) CD47-chimeric antigen receptor-T cell/Macrophages." (PMID 35418166, 2022). "Hence, the CD47-SIRPα signaling axis is an inhibitory checkpoint that bridges innate and adaptive immunity for tumor evasion." (PMID 35557862, 2022). "Consequently, the tumor cell overexpression of CD47 prompts its evasion from innate immunosurveillance." (PMID 35626039, 2022). "In conclusion, CD47 mAbs or SIRPα fusion combined with other anti-tumor drugs could be an effective treatment option for AML or MDS patients." (PMID 35978372, 2022). "Upregulated expression of CD47 on tumor cells increases the interaction with SIRPα on the myeloid cell membrane, leading to a release of the “don’t eat me” signal to evade the phagocytosis of myeloid cells, which is one of the primary mechanisms of cancer and disease formulation." (PMID 35557862, 2022). "The CD47-SIRPα axis reduces ability of TAMs to recognize and phagocytose tumor cells." (PMID 35672862, 2022). "This review summarizes the immune checkpoint and other receptor-ligand interaction between macrophages and tumor cells, which plays an indispensable role in anti-tumor immunity or pro-tumor immunity, such as SIRPα-CD47, PD1-PD-L1, FcγR-Antibody-Antigen, CSF-1/CSF-1R axis." (PMID 36497444, 2022). "Furthermore, the combination of LNT-UA and anti-CD47 antibody (αCD47) at tumor site achieved the abscopal effect in mouse bilateral CRC model, which would ultimately prolong survival of the host." (PMID 36168633, 2022). "As DCs appear to play a pivotal role in the cross-priming of antitumor T-cell response mediated by anti-CD47 mAb, we investigated whether NI-1701-induced tumor cell phagocytosis by DCs could trigger antigen cross-presentation to T cells." (PMID 35538512, 2022). "TIM3 and CD47 are highly expressed on tumor stem cells and could be used as markers for appreciating the maintenance of this cell population under exogenous stress." (PMID 35628503, 2022). "Similarly, E. coli expressing CD47 antagonist was reported to exert durable anti-tumor efficacy of the established A20 tumors." (PMID 35757741, 2022). "In addition, previous studies have demonstrated that the phagocytic activity of macrophages against tumor cells can be boosted through blocking the CD47-SIRPα interaction." (PMID 35869130, 2022). "Tumour cells overexpress CD47 and therefore evade the macrophage component of immune surveillance." (PMID 35954487, 2022). "Indeed, the blockade of the SIRPα/CD47 pathway reportedly potentiates T cell recruitment into tumor nest and antitumor immune activity in some tumor types." (PMID 35241649, 2022). "Conversely, we classified HCC patients into either high- or low-risk groups based on prognostic PRLs signature and showed that PD-1 and CD47 were highly expressed in tumor tissues, which may serve as candidate immune checkpoints." (PMID 35559014, 2022). "Moreover, αCD47 can be intratumorally injected in mice after the delivery of the vesicles and laser irradiation to block CD47, which is a ‘don’t eat me’ signal overexpressed on the surface of tumor cells that prevent their phagocytosis by DCs." (PMID 35335881, 2022). "However, to date, a detailed analysis of CD47 expression in both tumor cells and TIICs has been missing." (PMID 36171566, 2022). "Therefore, blocking the CD47/SIRPα cross talk activates the innate and adaptive immune systems, leading to tumor cell destruction." (PMID 35978372, 2022).
tumor (continued). "Furthermore, phenotypic analyses of CRC CTCs have identified CD47 as the predominant molecule upregulated in CTCs compared to the primary tumor, thereby protecting them from attack by myeloid cells." (PMID 36436127, 2022). "Similarly, the increased expression of CD47 is involved in another tumor-evasion mechanism, in which interaction with its receptor signal regulatory protein-α (SIRP-α) triggers an inhibitory “do not eat me” signal for phagocytic immune cells." (PMID 36009390, 2022). "In fact, preclinical studies in mouse models have shown that inhibition or blockade of CD47 inhibits tumor growth and enables the phagocytosis and killing of tumor cells by macrophages in several types of tumors, including ovarian, endometrial, liver, and squamous cell lung cancer, respectively." (PMID 35053602, 2022). "There are several mechanisms responsible for CD47 involvement in tumor progression." (PMID 35054787, 2022). "Surprisingly, both CD24 and CD47, two classic ligands of “don’t eat me” signal, were notably upregulated on tumor cells from mice received anti-CD20 antibody, whereas comparable expression levels of their receptors were observed on macrophages, Siglec-10 and SIRPα, respectively (Data not shown)." (PMID 36249034, 2022). "CD47 as another immune checkpoint is also overexpressed on the most tumor cells, and it often interacts with signal regulatory protein α (SIRPα) on phagocytic cells, which activates “don’t eat me signal” of CD47 and leads tumor cells to escape from immune monitoring." (PMID 36733388, 2022). "Additionally, high CD47 expression correlated with an immunosuppressed tumor microenvironment of exhausted CD8+ T cells." (PMID 36291980, 2022). "Single-cell RNA sequencing studies revealed that CD47 targeting induces compartmental remodeling of tumor-infiltrating immune cells within the PDAC tumor microenvironment by increasing the abundance of tumoricidal pro-inflammatory TAMs and reducing anti-inflammatory macrophages." (PMID 34201127, 2021). "In addition, the role of the immune environment in tumor progression has been emphasized, and many studies have focused on the immune-suppressive effects of the CD47-SIRPα axis, which is mediated by cancer cells and macrophages." (PMID 33917794, 2021). "Interestingly, the expression of PD-L1 and CD47 was significantly higher on CSCs than on tumor cells." (PMID 34203877, 2021). "Based on this, modulation of CD47 expression might have a dual effect, on one side induces a less aggressive tumor phenotype and, on the other side, HCC cells might become more susceptible to the recognition by the immune system." (PMID 33737571, 2021). "Hence, it is possible to restore TAM recognition and phagocytosis of tumor cells and to activate anti-neoplastic immune responses by interfering with the SIRPα-CD47 axis (e.g., by using antibodies to SIRPα and CD47)." (PMID 34178692, 2021). "It is evident that high expression of CD47 promotes tumor invasion and metastasis through Cdc42, and the level of CD47 is associated with tumor stage and lymph node and distant metastasis, especially in NSCLC; therefore, CD47 can be used as a biomarker for the prognosis of NSCLC." (PMID 34367975, 2021). "In addition to promoting the phagocytosis of live tumor cells by blocking CD47/SIRPα interaction, inhibiting the phagocytosis of apoptotic tumor cells by TAMs is another promising tumor immunotherapy strategy." (PMID 33919979, 2021). "Furthermore, anti-CD47 antibody treatment increased microglial infiltration and tumor phagocytosis even in CCRRFP/RFPCX3CR1GFP/wt mice in which macrophage infiltration into tumors was absent." (PMID 34685535, 2021). "The ability of TSP1 signaling via CD47 to inhibit Myc levels in T cells may contribute to metabolic reprogramming that limits cytotoxic T cell function in the tumor microenvironment." (PMID 33925464, 2021).
tumor (continued). "Through directly induced tumour cell death and activated phagocytosis of macrophages, the blocking of CD47 effectively facilitated the eradication of tumour cells and the subsequent cross‐priming of tumour‐specific cytotoxic T cells to activate the adaptive immune response." (PMID 33449453, 2021). "In many sarcomas, including chordomas, dedifferentiated liposarcomas, and osteosarcomas, CD47 was observed to be highly expressed on tumor cells along with SIRPα expression on macrophages, suggesting a means of immune evasion in these tumors through this inhibitory axis." (PMID 34440251, 2021). "CD47 staining in PanNETs was diffuse in all tumor cells with membranous and cytoplasmic staining." (PMID 33765961, 2021). "The effect of inhibiting CD47 in signaling pathways, other than SIRPα, is less studied and might be different according to tumor type." (PMID 34195295, 2021). "Another mediator of tumor immune evasion in addition to TAMs is the CD47/SIRPα axis." (PMID 34573091, 2021). "CD47 constitutively associates with VEGFR2 on endothelial and tumor cells." (PMID 33869231, 2021). "Additionally, DC express the SIRPα receptor and the leukocyte immunoglobulin-like receptor B1 (LILRB1), which, respectively, recognize CD47 and MHC class I-associated β2M subunits at the surface of tumor cells, blocking phagocytosis." (PMID 33418996, 2021). "Human tumor expression of CD47 has been shown to correlate with the expression of various co-inhibitory markers, such as program cell death protein 1 (PD-1) and cytotoxic T-lymphocyte associated protein 4 (CTLA-4), on tumor-infiltrating CD4+ and CD8+ T cells." (PMID 34603322, 2021). "In addition, tumor type and stage, tumor immune microenvironment and acquired drug resistance, constitute other potential determinants of the efficacy of CD47/SIRPα inhibitors." (PMID 34944850, 2021). "A antitumor peptide RS17 targeted CD47, Design, Synthesis and Anti‐Tumor activity." (PMID 33629544, 2021). "CD47+ CTCs have also been found to be responsible for tumour relapse and metastasis in patients with breast cancer, suggesting that the CTCs may also use this surface marker for colonisation." (PMID 33789677, 2021). "In addition, immunoliposome (ILips) combined with anti-CD47 and paclitaxel also produced a synergistic anti-tumor effect on converting M2 to M1 and enhancing systemic T cell immune response." (PMID 34717710, 2021). "Further studies have found that CD47 can affect the polarization of tumor‐associated macrophages, while CD24 has no relevant reports." (PMID 34363319, 2021). "CD47 is an anti-phagocytic receptor overexpressed in several human cancers and its blockade not only increases phagocytosis of cancer cells in vitro but also promotes activation of T cells against tumours in vivo." (PMID 34658896, 2021). "synthesized exosome nano-bio-conjugates through biosynthesis and, after systemic administration, specifically identified aCD47 and CD47 on the surface of tumor cells, demonstrating that nano-bio-conjugates could actively target tumor cells." (PMID 33828985, 2021). "However, combined with other therapies, CD47 blockade is able to enhance tumor volume control and extend response to treatment." (PMID 33748077, 2021). "CPMV VNPs have also been administered in combination with CD47-blocking antibodies which proved to have synergistic effects in combating tumor growth in murine ovarian tumor models, where it activated phagocytes, leading to stimulation of the adaptive immune response." (PMID 34976959, 2021). "Moreover, in some subsets including CD8 TEM, SU increased the level of tumor immunity-related genes, including CD47, PCBP2, EIF5A, and PDIA3." (PMID 34824394, 2021). "Moreover, disruption of the CD47/SIRPα axis reduces the ability of tumor cells to escape phagocytosis." (PMID 34573091, 2021).
tumor (continued). "Furthermore, MNPs coated by a silica layer conjugated with anti-CD47 antibody were subsequently magnetically guided to be accumulated at metastatic tumor sites to block the interaction of tumor-expressed CD47 with macrophages." (PMID 34675914, 2021). "For example, in phase I clinical trials of advanced solid tumors and blood cancers, CC-90002, an anti-CD47 antibody, is used to block over-expressed CD47 on cancer cells, thereby inhibiting the CD47-SIRPα signaling pathway and enhancing the phagocytosis of tumor cells by macrophages." (PMID 34683963, 2021). "Notably, CD47 is a cancer-related surface protein whose expression prevents recognition of cancer cells by the innate immune system, thus facilitating tumor progression." (PMID 33803776, 2021). "Resident microglia are present within the brain, but it is the recruitment of peripheral macrophages to the GB TAM pool, in particular, that may mediate tumor phagocytosis with disruption of the signal regulatory protein α receptor (SIRP-α)–CD47 axis." (PMID 34439159, 2021). "Due to biomimetic membrane camouflage and CD47 overexpression, meTGCT exhibited superior immune escape and homologous targeting capacities, which could effectively enhance the tumor preferential targeting and internalization." (PMID 34882297, 2021). "CD47 can trigger evasion of tumor cells from macrophage recognition by interacting with signal regulatory protein alpha (SIRPα), has been another hot target for tumor immunotherapy." (PMID 34288805, 2021). "Following treatment, CD47 was immediately modulated in the tumor compared to untreated." (PMID 33540720, 2021). "This has been investigated by Daldrup-Link and coworkers where combination of doxorubicin and CD47 mAb significantly inhibited tumor growth and improved survival in a manner proportional to the increase in iron metabolism that was detected by increases in TAM iron using histology and MRI." (PMID 33986740, 2021). "CD47, as an inhibitory receptor on the surface of tumor cells, can interact with the signaling protein SIPR-α on the surface of the cell membrane, which may mediate immune escape from macrophages and T cells." (PMID 33828985, 2021). "In the case of BCa, it was shown that CD47 was expressed by at least 80% of tumor cells." (PMID 34572939, 2021). "Furthermore, oncogenic signaling through MYC enhances the expression of CD47 and PD-L1 on tumor cells." (PMID 33859752, 2021). "CD47 also leads to cell death in normal and tumor cells via apoptosis or autophagy." (PMID 33936211, 2021). "In conclusion, we have unveiled a previously unknown activity of CXCR4, which by co‐internalizing CD47 exposes tumor cells to immunosurveillance." (PMID 33956406, 2021). "The tumor CSC phenotype expressing CD47 has a higher degree of invasiveness and metastasis." (PMID 34205080, 2021). "The engagement of tumor cell CD47 with SIRPα expressed on the surface of monocytes/macrophages may produce inhibitory signals which inhibit phagocytosis." (PMID 33629544, 2021). "These indirect effects may contribute to the anti-tumor and pro-inflammatory activity of CD47 inhibition." (PMID 34944850, 2021). "This review expands on the immunological mechanisms of 17 immune checkpoints, including TIM-3, CD47, and OX-40L, that mediate tumor metastasis; evidence shows that most of these immune checkpoints are expressed on the surface of T cells, which mainly exert immunomodulatory effects." (PMID 34367975, 2021). "BsAbs co-targeting CD47 and other tumor-specific antigens may improve the binding specificity of CD47-directed antibody, thus enhancing safety and efficacy." (PMID 34305918, 2021). "The beneficial effect of anti-CD47 immunotherapy was confirmed in other tumor models." (PMID 34572939, 2021). "This shift in central carbon metabolism activated highly phagocytic macrophage that could overcome the CD47 “don't-eat-me” signals on tumor cells to mediate an antitumor response." (PMID 33968034, 2021).